FOXA1 (forkhead box A1)
Diseases named in the same sentence as FOXA1 in open-access papers (continued):
Sharing a sentence is not in itself a finding about the gene and the disease.
breast carcinoma (continued). "Immunohistochemical analysis of FOXA1 and Nestin expression in breast cancer metastases revealed FOXA1-positivity and Nestin-positivity in 52 and 16% of the metastatic samples, respectively." (PMID 30819139, 2019). "A recent study showed that TLE3 suppresses target genes of estrogen receptor alpha (ERα) by interacting with FOXA1 in breast cancer MCF-7 cells." (PMID 31569653, 2019). "Recent data suggest that KMT2D is involved in the recruitment and activation of relevant breast cancer genes including FOXA1, PBX1, and ER." (PMID 30990809, 2019). "This is the first report, to our knowledge, showing FOXA1 and Nestin expression in breast cancer metastases." (PMID 30819139, 2019). "To determine the role of FOXA1 in the development, progression, and prognosis of breast cancer, we analyzed extensive gene expression data with well-defined parameters in breast cancer and normal samples." (PMID 31562808, 2019). "The relationship between mRNA expression of FOXA1 and clinicopathological parameters of breast carcinoma." (PMID 31562808, 2019). "It has also been explained that the lack of FOXA1 expression leads to decreased breast cancer cell proliferation." (PMID 30054444, 2019). "FOXA1 promotes E-cadherin expression on the protein level by suppressing Slug expression in breast cancer, suggesting that the balance of Foxa1-slug axis regulates EMT-progression." (PMID 30819139, 2019). "A third recently described role of CAFs is their induction of a FOXA1‐mediated creation of a hormone‐sensitive, luminal gene regulatory program in basal‐like breast cancers in response to PDGF secretion by the tumor cells." (PMID 31304632, 2019). "Breast cancer metastases (n = 164) from various anatomical sites were retrospectively analyzed by immunohistochemistry for FOXA1, Nestin and GATA3 expression." (PMID 30819139, 2019). "This included 7 breast cancer-related genes: caspase 8 (CASP8), cadherin 1 type 1 (CDH1), estrogen receptor 1 (ESR1), ETS variant 6 (ETV6), forkhead box A1 (FOXA1), GATA-binding protein 3 (GATA3) and neurotrophic tyrosine kinase receptor type 3 (NTRK3)." (PMID 31182966, 2019). "FOXA1 is the primary determinant of ER binding and transcriptional activity in breast cancer cells and therefore is probably related to the response to endocrine therapy." (PMID 31562808, 2019). "FOXA1 is an established pioneer factor for the majority of ERα binding to the genome in human breast cancer cells." (PMID 31408468, 2019). "We examined the expression profile of FOXA1 across PAM50 breast cancer subtypes using 5861 patients in bc-GenExMiner 4.0 based on clinical-pathological parameters." (PMID 31562808, 2019). "Our own results demonstrated the upregulation of FOXA1 mRNA expression and better probabilities of survival in breast cancer." (PMID 31562808, 2019). "Our results demonstrated that the expression of FOXA1 is affected by methylation and ER+ tumor status and is related to prognosis in breast cancer." (PMID 31562808, 2019). "SAGE data showed that FOXA1 was overexpressed in breast cancer tissues compared with matched normal tissues." (PMID 31562808, 2019). "FOXA1 mediates ESR1 binding and transcriptional activity, and its expression is associated with superior breast cancer outcomes." (PMID 31304632, 2019). "As expected and in line with literature, most ERα‐positive primary breast cancers we studied also expressed FOXA1 (n = 73/81, 90%; staining percentage range 3–100%, mean 70%) and GATA3 (n = 63/81, 78%; staining percentage 1–100%, mean 58%)." (PMID 29972720, 2018). "In breast cancer cells, FOXA1 is needed to reprogram the genomic binding profiles of estrogen receptor following ligand activation." (PMID 28681081, 2018). "This work has characterized the DNA binding landscape of ERα in male breast cancer, along with its pioneer factors FOXA1, GATA3, and enhancer-enriched histone modification H3K4me1." (PMID 29396493, 2018).
breast carcinoma (continued). "This approach identified SNVs in breast cancer samples within the regulatory regions of FOXA1, RMRP, and NEAT1 that affect gene expression levels." (PMID 29456552, 2018). "While it also has been suggested to be a transcription activator which induces target gene FOXA1 transcription by binding to its promoter in human breast cancer cells." (PMID 29601666, 2018). "As such, both GATA3 and FOXA1 are termed key luminal breast cancer‐defining genes and are expressed in virtually all ERα‐positive primary breast cancers." (PMID 29972720, 2018). "Although GATA3 levels remained unaltered between primary breast cancer and pleural metastases, FOXA1 levels were reduced exclusively in metastases of patients who received endocrine therapies in the adjuvant setting, even though ERα was still expressed." (PMID 29972720, 2018). "For this aim, we took a high throughput chemical screening approach (with known protein targets) in order to search for proteins controlling FOXA1 in breast cancer cells." (PMID 30572598, 2018). "Interplay between FOXA1 and breast cancer specific signaling pathways has been reported previously, indicating a regulation network on FOXA1 in breast cancer cells." (PMID 30572598, 2018). "Together, our CRISPR rat Nf1 model and our WGCNA analysis of human breast cancer confirms that NF1 is intricately connected to ER networks, including several genes that have been directly linked to endocrine resistance (i.e., FOXA1 and AR)." (PMID 30182054, 2018). "Cumulatively, these data illustrate that FOXA1 expression is decreased in progressive metastatic breast cancer to the pleural cavity." (PMID 29972720, 2018). "FOXA1 was found increased in metastatic breast cancers in relation to the primary tumor, but a comprehensive clinical assessment thereof, in relation to different metastatic sites and endocrine therapy usage, is currently lacking." (PMID 29972720, 2018). "The role of forkhead-box A1 (FOXA1) and Androgen receptor (AR) in breast cancer (BC) has been extensively studied." (PMID 29970021, 2018). "Consistent with the results of liver developmental studies, one member of the FoxA family, FOXA1, works as a pioneer factor in the AR and estrogen receptor (ER) pathways in prostate cancer and breast cancer cells." (PMID 28264478, 2017). "For instance, FOXA1 is high expression in multiple cancers, including pancreatic cancer, glioma cancer, breast cancer, prostate cancer and bladder cancer." (PMID 29050292, 2017). "That possibility is supported by our observations that FoxM1 inhibits expression of the differentiation genes GATA3 and FoxA1 in breast cancer cells." (PMID 28387346, 2017). "Fittingly, in mouse prostate tumor cells, FOXA1 and SNAIL2/SLUG reciprocally repress each other, and FOXA1 was reported to stimulate promoter activity of the epithelial marker gene CDH1 (coding for E-CADHERIN) in human breast cancer cells." (PMID 29155818, 2017). "Recently, the dual roles of FOXA1 in breast cancer as a growth stimulator and inhibitor have been considered controversial." (PMID 29137314, 2017). "And the levels of FOXA1 protein have been correlated with the prognosis of breast cancer and gastric cancer." (PMID 27974698, 2017). "FOXA1 correlates with survival duration in female breast cancer, where cases with high expression had significantly better survival." (PMID 28350011, 2017). "As FOXA1 is emerging as a critical player in breast cancer biology we examined the impact of its co-expression with AR and ERβ isoforms on survival in an ERα+ background." (PMID 28350011, 2017). "Using breast cancer patient population treated at a single institute, the prognostic value of immunohistochemically determined AR and FOXA1 status was investigated." (PMID 29137314, 2017). "GATA3 was found to act upstream of FOXA1 in mediating ESR1 binding by analyzing ChIP-seq-binding signals in breast cancer cells." (PMID 29051499, 2017).
breast carcinoma (continued). "Particularly, our model correctly prioritized SNPs that are proved to be enriched for the binding sites of FOXA1 in breast cancer cell lines from previous studies." (PMID 28361702, 2017). "In this study, we demonstrated that ER(α), GATA3 and FOXA1 form a transcriptional complex with Ell3 to regulate IL-20 expression in ER(+) breast cancer cells." (PMID 28514748, 2017). "Amplification of FOXA1 gene has been found in lung cancer, esophageal adenocarcinoma, estrogen receptor (ER)-positive breast cancer and anaplastic thyroid cancer." (PMID 27974698, 2017). "Recent meta-analyses of breast cancers demonstrated that high FOXA1 levels were positively correlated with ER-positive and progesterone receptor (PR)-positive tumors." (PMID 29137314, 2017). "In this study, we show that Ell3, ER(α), GATA3 and FOXA1 form a transcriptional complex to regulate IL-20 expression in ER(+) breast cancer cell lines." (PMID 28514748, 2017). "GATA3 and FOXA1 are considered ER-related genes because they are co-expressed with ER(α) in breast tumors and in breast cancer cell lines." (PMID 28514748, 2017). "ER+, PR+, and FoxA1+ MECs belong to a class of “hormone-sensing” (HS) MECs thought to be directly involved in mammary differentiation and in some human breast cancers." (PMID 28865492, 2017). "We therefore chose to focus on FOXA1 for experimental validation of our results, and also SPDEF because it is a less well-studied, newly-identified ER+ breast cancer risk TF." (PMID 27997592, 2016). "Remarkably, four well-described differentiating proteins in breast cancer subtypes, namely, Her2, Grb7, FOXA1 and MLPH, were clearly selected in the PAM50 as well as in the proteomic signatures." (PMID 26725330, 2016). "Direct evidence suggests that FOXA1 regulates almost all estrogen receptor-chromatin interactions, thus influencing target gene expression levels in breast cancer cells." (PMID 27835577, 2016). "Both SPDEF and FOXA1 mRNA and protein were expressed in all three ER+ breast cancer cell lines, and their expression levels were significantly reduced following transfection of siRNA against the TFs." (PMID 27997592, 2016). "We applied the MINDy (Modulator Inference by Network Dynamics) algorithm to four TFs (ESR1, FOXA1, GATA3 and SPDEF) that are key drivers of estrogen receptor-positive (ER+) breast cancer risk, as well as cancer progression." (PMID 27997592, 2016). "The SNP rs4784227, a risk variant for breast cancer in Asian women, was also reported to alter TOX3 expression by disrupting enhancer function through FOXA1 affinity modulation." (PMID 27806084, 2016). "Since FOXA1 contributes to the establishment of enhancer elements that are subsequently used by transcription factors such as ER in these breast cancer cells, we integrated the MLL3, FOXA1, and GRHL2 ChIP-seq data with ER binding information." (PMID 27926873, 2016). "ESR1, GATA3 and FOXA1 form part of the well-characterised estrogen receptor transcriptional network in ER+ breast cancer cells." (PMID 27997592, 2016). "Since FOXA1 is known to colocalize with ER at enhancers, they believe the silencing of FOXA1 will effect ER action, ultimately leading to changes that contribute to the protective effect of parity against breast cancer." (PMID 27833901, 2016). "We first characterised SPDEF and FOXA1 expression and activity in three ER+ breast cancer cell lines (MCF-7, T47D and ZR751)." (PMID 27997592, 2016). "Recent evidence has shown that FOXA1 is essential for almost all ER binding events in breast cancer and for ER functionality, yet our understanding of FOXA1 activity and the events involved in determining FOXA1-chromatin interactions is limited." (PMID 27926873, 2016). "Several reports showed that FOXA1 expression levels significantly correlated with better breast cancer-specific survival." (PMID 27835577, 2016). "FoxA1 is a potent pioneer factor and is crucial for estrogen receptor (ER)-mediated transcription in breast cancer cells." (PMID 27374105, 2016).
breast carcinoma (continued). "Previous studies showed that the deregulation of FOXA1 played a potentially critical role in the carcinogenesis of breast cancer by disturbing ER binding." (PMID 27835577, 2016). "The DNA-binding protein FOXA1 has been shown to regulate nearly all estrogen receptor-chromatin interactions, thereby influencing target gene expression levels in breast cancer (BC) cells." (PMID 27835577, 2016). "ERα binding and activity in breast cancer is regulated and controlled by various other factors such as FOXA1, a pioneering factor required for binding of ERα and PR, a modulator of ERα action in breast cancer." (PMID 27129152, 2016). "We identified networks regulated by known cancer drivers such as GATA3 and FOXA1 (breast cancer), SOX17 and FOXA2 (endometrial cancer), and NFE2L2, SOX2, and TP63 (squamous cell lung cancer)." (PMID 25994056, 2015). "These in vivo data provide further proof that DNA methylation is a major mechanism for repressing FOXA1 expression in familial breast cancers and confirm a role for BRCA1 in regulating FOXA1 methylation and expression." (PMID 25531315, 2015). "Similar correlations between BRCA1 and FOXA1 expression were observed in a panel of breast cancer cell lines with different levels of wild-type BRCA1." (PMID 25531315, 2015). "Comparison of our signature with the Sorlie’s signature and PAM50 suggests the crucial roles played by FOXA1 in breast cancer classification." (PMID 26404658, 2015). "In our study, several genes of the top 10 down-regulated DEGs such as DUSP1, FOXA1, MLPH was implicated in the development of breast cancer." (PMID 26103053, 2015). "ER-α is an established driver of luminal breast cancer and FOXA1 is a pioneer factor that physically interacts with compacted chromatin, facilitating binding of ER-α, and is necessary for ER-α mediated transcription." (PMID 25652398, 2015). "The comparison of our signature with two pioneering signatures, the Sorlie’s signature and PAM50, suggests a novel marker, FOXA1, in breast cancer classification." (PMID 26404658, 2015). "We also went on to explore the potential molecular mechanism involved and identified FOXA1 as an EZH2-regulated gene in breast cancer cells." (PMID 25531315, 2015). "The good correlation between BRCA1 and FOXA1 expression in the panel of breast cancer cell lines led us to explore further the possibility that BRCA1 regulates FOXA1 expression." (PMID 25531315, 2015). "This growth factor has been shown to contribute to breast cancer progression and endocrine resistance through stabilization of FOXA1 protein in MCF-7 cells." (PMID 25632947, 2015). "In light of these findings, collectively, our results lead us to propose a mechanistic model in which BRCA1 can promote FOXA1 transcriptional expression and thereby, breast cancer luminal subtype development through targeting EZH2." (PMID 25531315, 2015). "Nevertheless, the breast cancer patient gene expression microarray and methylated DNA immunoprecipitation analyses clearly show that BRCA1 mutation is significantly associated with FOXA1 gene promoter methylation and expression downregulation." (PMID 25531315, 2015). "Outside of PC, FOXA1 has been demonstrated to be a vital regulator of ER signalling in breast cancer and therefore is a bona fide therapeutic target in this disease setting." (PMID 26336819, 2015). "Conversely, FOXA1 is a pioneer transcription factor and a recognized marker for luminal subtype of breast cancer." (PMID 25531315, 2015). "In agreement with cell line data, we found that PBX1 protein levels significantly correlate with ERα, FOXA1 and GATA3 (another important ERα pioneer factor) thus demonstrating that PBX1 is strongly associated with ERα-positive, luminal breast cancer subtypes." (PMID 26215677, 2015). "If FOXA1 is important for regulating ERα activity in endometrial cancer, as is seen in breast cancer, an overlap between the differentially expressed genes would be expected." (PMID 24849812, 2014).
breast carcinoma (continued). "These genes, FOXA1, GATA3, and MYB, all showed greater mutation rates in ER+/luminal cancers relative to other breast cancer subtypes and, here, possessed up-regulated expression in early neoplasias relative to normal." (PMID 24887547, 2014). "It is critical to note that the role of FOXA1, as a tumor oncogene or a tumor suppressor gene, has been reported to vary in prostate and breast cancers depending on multiple cancer subtypes and states of hormone dependence or independence." (PMID 24512546, 2014). "In breast cancer, FoxA1 expression is a significant predictor of cancer-specific survival in patients." (PMID 25512556, 2014). "Whilst recent data report upregulation of both FGFR3 and FOXA1 characterize the papillary (luminal breast cancer-like) molecular subtype of invasive UCC, these reports did not include low-grade tumors." (PMID 25071007, 2014). "Several proteins serve as pioneer factors contributing to ERα action in breast cancer, including FOXA1 and GATA3." (PMID 24962896, 2014). "This idea consists with breast cancer studies that have shown that FOXA1 functions as a tumor suppressor in ER-positive breast cancer cells (MCF-7) but as a tumor activator in ER-negative breast cancer cells (MDA-MB-453)." (PMID 24512546, 2014). "Comparing between MCF7 breast cancer and LNCaP prostate cancer cell lines, FoxA1 binds differentially to more than half of its target sites." (PMID 25512556, 2014). "Studies in breast cancer have shown that ERα positive patients with high expression of FOXA1 have a significantly better survival compared to patients with low expression of FOXA1." (PMID 24849812, 2014). "In breast cancer FOXA1 seems important for ER mediated transcription, and silencing of FOXA1 leads to inhibition of ER binding and transcriptional activity." (PMID 24849812, 2014). "For example, another TF, FOXA1 initiates ERα recruitment to promoter regions relevant to breast cancer and mediates epigenetic control of cell-type specific gene expression." (PMID 24792166, 2014). "FOXA1 has been recognized as an important transcription factor that modulates the functions of steroid receptors such as estrogen receptor in breast cancer and AR in prostate cancer." (PMID 24849812, 2014). "The low correlation between ERα and FOXA1 expression in metastatic lesions, suggests that FOXA1 is less critical for ERα function in endometrial cancer compared to what has been observed for breast cancer." (PMID 24849812, 2014). "In both prostate and breast cancers high expression of FOXA1 in metastatic lesions were found, however with retained expression of AR and ERα respectively." (PMID 24849812, 2014). "The binding of FOXA1 to the rs2981578 SNP locus was confirmed in MCF7, T47D and ZR75-1 cell lines by ChIP-seq data analysis from a study on FOXA1 and ERα function in breast cancer." (PMID 24265722, 2013). "FOXA1 is crucial in mediating the binding of ERα to its target genes, and whole genome ChIP-seq screening has demonstrated that FOXA1 plays a role in the reprogramming of ERα binding sites during breast cancer progression." (PMID 24265722, 2013). "The transcriptional regulator FOXA1 which is a mediator of estrogen signaling in ER-positive luminal breast cancer was found in the ten highest scoring genes." (PMID 24260093, 2013). "FOXA1 is required for global ER binding in the MCF7 breast cancer cell line and ER occupancy at >90% of binding events is reduced when FOXA1 is silenced, which correlates with a global loss in the accessibility of chromatin." (PMID 23420418, 2013). "FOXA1 expression positively correlates with ER and PR expression in breast cancer, and low expression of FOXA1 predicts poor prognosis for all patients and luminal subtype patients." (PMID 23620774, 2013).